INS (insulin)
Diseases named in the same sentence as INS in open-access papers (continued):
Sharing a sentence is not in itself a finding about the gene and the disease.
diabetes (continued). "In contrast to type 1 diabetes, patients with MODY have preserved pancreatic β-cells function and their diabetes is well controlled with no or low doses of insulin for at least 5 years after diagnosis." (PMID 35784568, 2022). "The same was confirmed in rats with streptozotocin-induced diabetes, treated and not treated with insulin." (PMID 34313900, 2022). "In terms of youth with obesity and insulin resistance (without diabetes), a BMI reduction of about 8% was the threshold, which improved insulin sensitivity was observed." (PMID 36387846, 2022). "The exact names of insulin analogs and the duration and nature of diabetes educational programs were not recorded." (PMID 35101023, 2022). "For example, in women without subsequent diabetes prior to outcome, a 30% increase in incident any CVMM risk was observed among women with previous insulin-treated GDM, compared to women with non-insulin-treated GDM." (PMID 36085031, 2022). "Diminished insulin secretion is characteristic of patients with diabetes in Asian countries, where BMIs of patients are not remarkably greater than those of the general population." (PMID 35010830, 2022). "Though many trials had examined the effectiveness of taking insulin with or without oral agents, there are limited real-world data, particularly among patients with type 2 diabetes mellitus (T2DM) in the resource limited settings." (PMID 35617250, 2022). "These patients present diabetes at adulthood and usually do not require insulin therapy immediately after their diagnosis, as they present primarily with symptoms and signs of type 2 DM (T2DM)." (PMID 35918735, 2022). "Diabetes is a disease characterized by a relative or absolute lack of insulin, leading to hyperglycemia." (PMID 35463673, 2022). "It has been documented that poor dietary intake, coupled with a lack of physical activity and exogenous insulin therapy administration, are responsible for weight gain among people with diabetes." (PMID 36360448, 2022). "In the Chow-diabetes group and the HFD plus diabetes group, as expected, blood glucose levels were elevated in each and they were also insulin resistant as shown with a greater glucose area under the curve (AUC) value than Chow fed mice when subjected to an ITT." (PMID 35038159, 2022). "Thus, apocynin also improved insulin tolerance in diabetic rats, as shown by significant decreases in glucose levels and the area under the ITT curve in the diabetes + apocynin group compared with the diabetes group (P < 0.01)." (PMID 35629342, 2022). "In individuals with diabetes, there is either less/no production of insulin (type-1) or resistance to the reception of insulin by its receptors (type-2)." (PMID 35684464, 2022). "Future research should aim to identify the appropriateness of insulin therapy specifically in patients without diabetes presenting with hypertriglyceridemia and the dosing associated with optimal safety." (PMID 36203643, 2022). "Like diabetes, prediabetes is characterized by impaired glucose tolerance; however, those with prediabetes show slight elevations in insulin and fasting blood glucose, rather than hyperglycemia." (PMID 35568928, 2022). "Patients who failed to withdraw from insulin despite high ΔCPR were characterized by older age and longer duration of diabetes." (PMID 35574023, 2022). "When our body is not able to produce sufficient insulin or cannot use it effectively, diabetes occurs." (PMID 35406580, 2022). "Moreover, fasting insulin and HOMA-IR were higher in diabetes participants with MCI than in those with normal cognition." (PMID 35682821, 2022). "In animal models, elevated LPC levels have also been observed in insulin autoantibody-positive female NOD mice that did not develop diabetes compared with progressors." (PMID 36329300, 2022). "While insulin is often a mainstay of diabetes treatment for effective blood glucose control, many Latinx individuals have negative feelings toward the use of insulin." (PMID 35444916, 2022).
diabetes (continued). "In insulin-dependent tissue systems (e.g., skeletal muscles, adipocytes, hepatocytes and pancreases), there are paradoxical data regarding PHLPP isoform specific expression under pathological conditions like diabetes and obesity." (PMID 36376971, 2022). "Patients with diabetes mellitus were treated with oral antidiabetics (100% in the first group and 88.47% in the second group) or insulin (none in the first group and 11.53% in the second group)." (PMID 35741309, 2022). "The underlying pathophysiological mechanisms behind this bidirectional relationship between diabetes and depression are not fully elucidated but inflammatory mechanisms and insulin resistance seem to play an important role." (PMID 35253006, 2022). "Of the two types of diabetes, type I diabetes is an autoimmune disease that involves the destruction of beta cells in the pancreas, resulting in little to no insulin production." (PMID 36072265, 2022). "Sixteen weeks of daily treatment with NSI-189 did not affect blood glucose or reduced insulin levels at 40 weeks of diabetes." (PMID 35967127, 2022). "MPC1 is expressed in many organs, and we here present the first individual with the additional features of splenomegaly, bone fractures after minor trauma and insulin-dependent, anti-body negative diabetes mellitus." (PMID 36079864, 2022). "When insulin secretion no longer meets metabolic demand, blood glucose continues to rise to a level where frank diabetes is diagnosed." (PMID 36144859, 2022). "It is the first therapeutic choice for Type 2 Diabetes Mellitus, since it inhibits hepatic gluconeogenesis and prevents hyperglycemia without impairing insulin secretion, hypoglycemia, or weight gain.It has been used for more than four decades." (PMID 36518134, 2022). "In addition, Polygonatum also improves homeostasis model assessment of insulin sensitivity (HOMA-IS) and homeostasis model assessment of insulin resistance (HOMA-IR) of patients with diabetes in clinical studies." (PMID 35211009, 2022). "Soon after, Sharpey-Schafer posited that diabetes developed due to a lack of a substance in the pancreas, which he called insulin." (PMID 34991585, 2022). "Diabetes is a serious, chronic disease that occurs either when the pancreas does not produceenough insulin or when the body cannot effectively use it." (PMID 37432671, 2022). "However, some studies report a negative correlation between cognitive performance and fasting insulin and HOMA-IR in non-diabetes participants with hyperinsulinemia and insulin resistance (IR)." (PMID 35682821, 2022). "Our study aimed to assess patients with non–insulin-treated DMT2 who were receiving care from a single clinic and analyze whether the use of a diabetes management app and SMBG behavior would affect glycemic control in a real-world clinical setting." (PMID 35704371, 2022). "This suggests that having more time to focus on diabetes management, fine-tuning the pump, and having parents more involved in the daily diabetes treatment benefits especially those children treated with insulin pumps without hybrid closed loop –algorithm." (PMID 35045807, 2022). "Diabetes is a chronic condition that arises when the pancreas does not create enough insulin or when the insulin produced is not used efficiently by the body." (PMID 36544136, 2022). "Increased inflammation triggered by dietary factors, such as copper, can impair insulin signaling and promote diabetes risks as observed in our nondiabetic controls." (PMID 35789593, 2022). "Diabetes mellitus is a chronic disease that occurs when the beta cells located in the pancreas produce insufficient or no insulin." (PMID 36078223, 2022). "Multivariate linear regression confirms a significant association between insulin sensitivity and a higher concentration of NDUFS8 in serum (beta = 0.54, p = 0.003), independent of age, duration of diabetes, and smoking." (PMID 36135178, 2022).
diabetes (continued). "Decreased expression of this gene causes a lack of response to glucose, decreased glucose-stimulated insulin secretion, and increased β-cells apoptosis and diabetes." (PMID 35725834, 2022). "Intermittent fasting/exercise‐related elevated serum irisin has been connected to improved metabolic health, insulin signaling, glucose homeostasis, and other glycemic profile in animal STZ‐models of diabetes, making it a prospective target in the management of metabolic diseases." (PMID 36305681, 2022). "Therefore, we inferred that the increased rate of DM in GG genotype carriers of rs12025144 could be mediated by the insulin-dependent diabetes gene; however, its exact role requires further exploration." (PMID 36362461, 2022). "The second patient (patient #28) with newly diagnosed diabetes had impaired insulin secretion and failed to lower glucose levels to a normal range, indicating an insulin resistance." (PMID 35343389, 2022). "A sensitivity analysis which excluded people with diabetes who were taking oral glucose-lowering drugs, with or without insulin, or had missing information regarding glucose-lowering therapies, showed that the outcomes were essentially unchanged." (PMID 36079764, 2022). "Diabetes mellitus (DM) is one of the most common chronic diseases in the world, and it is characterized by high levels of glucose in the blood due to a lack of insulin secretion and/or action." (PMID 36579585, 2022). "Type 1 diabetes is characterized by a lack of or near-lack of b-cells, so insulin is necessary for people with this type of diabetes." (PMID 36556420, 2022). "Type 1 diabetes mellitus (T1DM) is a chronic autoimmune disease that tends to occur in children and adolescents, resulting from autoimmune degradation of pancreatic β cells leading to lifelong dependence on exogenous insulin." (PMID 36090587, 2022). "In our study, type 2 diabetic subjects with DFD were older, with longer duration of diabetes, had more micro- and macro-vascular complications, and were more often treated with insulin and antiplatelet agents than those without DFD." (PMID 36353236, 2022). "The present study excluded patients with known diabetes, wherefore patients with hypoglycemia should not have received any insulin treatment in relation to the blood glucose level at ED admission." (PMID 36435766, 2022). "LADA refers to a type of diabetes that is characterized by slowly progressing autoimmune damage to islet beta cells in the early clinical stages without the need for insulin therapy." (PMID 36090989, 2022). "At baseline, 53 of 65 patients (81.5%) were diagnosed with T2DM (mean duration of diabetes, 9.7 ± 7.3 years); 20 of the patients with T2DM (37.7%) were receiving insulin treatment, whereas 45 (84.9%) were on glucose-lowering agents, with a mean elevated HbA1c of 7.5%." (PMID 35956083, 2022). "Upregulation of PEPCK, the rate limiting enzyme of gluconeogenesis, takes place in almost all diabetes models as a result of a lack of insulin and/or its action." (PMID 36160451, 2022). "Since the gut hormone ghrelin may be involved in glucose homeostasis via inhibition of insulin secretion, administration of Bifidobacterium longum APC1472 may be clinically significant in patients with pre-diabetes and type 2 diabetes mellitus." (PMID 36013366, 2022). "Diabetes mellitus is a chronic metabolic multifactorial disorder accompanied by altered macro-nutrient metabolism, due to the lack of insulin activity, or inability to use insulin properly." (PMID 35807304, 2022). "This insulin can be used to control diabetes mellitus effectively in dogs, including some dogs in which lente insulin was not successful, presumably reflecting the longer duration of action." (PMID 35152907, 2022). "Studies on HRQOL in nation-based pediatric diabetes populations, using modern insulin delivery and glucose monitoring devices, are lacking." (PMID 36387938, 2022).
diabetes (continued). "People with diabetes who do not have enough insulin or cannot respond to it will have hyperglycemia and impaired autophagy." (PMID 35268815, 2022). "Studies in subjects with type 2 diabetes mellitus (T2DM) who have impaired insulin secretion suggest that decreased GLP-1 secretion and/or action may play a role in diabetes pathogenesis." (PMID 35099411, 2022). "Although R6/1 displayed some signs of impaired glucose tolerance (including abnormal glucose handling and higher glucose plasma and insulin levels in the glucose challenge), it did not manifest as diabetes due to normal peripheral insulin sensitivity." (PMID 36078070, 2022). "Although we did not focus on type 2 diabetes and diabetes remission, modification of insulin resistance is highly relevant, as improvement of insulin sensitivity is a crucial element in remission of type 2 diabetes." (PMID 35897098, 2022). "Adults with insulin-treated type 1 and type 2 diabetes, inadequate glycemic control, and no severe diabetes-related complications and/or comorbidities were eligible for this study." (PMID 35476320, 2022). "However, individuals with type 1 diabetes mellitus (T1DM) or type 2 diabetes mellitus (T2DM) exhibit hyperglucagonemia and hyperglycemia because of insufficient insulin secretion or insulin resistance." (PMID 35571202, 2022). "Despite the advances of insulin therapy, many patients with T1D do not reach the glycemic control necessary to prevent the progression of diabetes complications." (PMID 35456818, 2022). "Although Mafa-deficient mice have a comparable number of β-cells throughout embryonic development and at birth, they become intolerant to glucose with reduced or no expression of insulin in the islets, although they do not show overt diabetes." (PMID 35562869, 2022). "Diabetes mellitus is a diverse metabolic disease described by hyperglycemia due to a relative or absolute lack of insulin." (PMID 35890680, 2022). "As a result of insufficient insulin production in the body (Type-1 diabetes) or not being able to use the insulin produced in the body (Type-2 diabetes), diabetes is defined by hyperglycemia, or a high blood glucose level." (PMID 36421123, 2022). "The notable canonical pathways shared between both CUR groups in the different dietary regimens included insulin secretion and insulin receptor signaling pathways, the senescence pathway, IGF-1, mTOR, and Hif1 α signaling, and Type 2 diabetes mellitus signaling." (PMID 35017319, 2022). "As well, STZ-induced diabetes did not alter the pattern of distribution between Rab11A and glucagon, but did decrease the colocalization between insulin and Rab11A." (PMID 34923907, 2022). "Regarding diabetes and its complications, there is a new trend towards the recognition of PRL as an important metabolic hormone, directly involved in beta-cell function and survival, and the regulation of insulin sensitivity and resistance, respectively." (PMID 36157442, 2022). "The complications of diabetes reflect dysfunction or death of cell types that are highly permeable to glucose in the absence of effective insulin activity." (PMID 36135209, 2022). "In studies of Japanese pedigrees, there was evidence of insulin and non-insulin-treated diabetes within pedigrees; in 1 family, 2 patients presented with diabetic ketoacidosis, whereas other relatives were non-insulin dependent." (PMID 35552684, 2022). "The OpenAPS Data Commons dataset, donated to by open-source AID users with insulin-requiring diabetes, is the largest freely available diabetes-related dataset with over 46,070 days’ worth of data and over 10 million CGM data points, alongside insulin dosing and algorithmic decision data." (PMID 35565875, 2022). "In an insulin sensitizing drug study, it was reported that in contrast to metformin, particularly in individuals without diabetes, glitazones showed significant histological and biochemical benefits in patients with NAFLD." (PMID 35999630, 2022).
diabetes (continued). "For this reason, cases of WS2 using diabetes technologies (glucose sensors and insulin pumps) are not described by literature and self-blood glucose monitoring is performed by these rare pediatric patients who are affected by diabetes." (PMID 35055657, 2022). "Barriers to diabetes self-management include a lack of healthy food options at shelters and safe medication (including insulin) storage." (PMID 36992789, 2022). "Diabetes mellitus is a chronic disease that occurs when the pancreas fails to produce sufficient insulin to regulate blood sugar or when the body is unable to use the insulin produced effectively." (PMID 36551103, 2022). "This is consistent with the observation that diabetic patients treated with insulin have significantly lower plasma TRAIL concentrations in comparison with either diabetic patients not treated with insulin or those without diabetes." (PMID 34313900, 2022). "Type 1 diabetes mellitus (T1DM) accounts for approximately 5–10% of all patients with DM, and it results from pancreatic beta cell dysfunction with reduced insulin secretion, while type 2 DM (T2DM) is related to insulin resistance and accounts for 90–95% of all diabetic patients." (PMID 36291558, 2022). "Diabetes occurs when the body is not able to produce enough insulin (T1D) or when the body cannot effectively use the insulin that is being produced (T2D)." (PMID 35992116, 2022). "There are two major types of diabetes: the pancreas does not produce insulin in Type 1, whereas in Type 2 the body cells are resistant to the action of insulin that is being produced and over time the production of insulin progressively decreases." (PMID 35455483, 2022). "Insulin administration (IA) and blood glucose monitoring (BGM) either by self-monitoring of blood glucose (SMBG) or continuous glucose monitoring (CGM) practices are the key components of the diabetes self-care regimen for T1D." (PMID 38515508, 2022). "Subjects with prediabetes/diabetes had higher BMI, waist circumference, systolic and diastolic blood pressure, fasting and post-OGTT glucose and insulin, HOMA-IR and lower QUICKI and Matsuda index in comparison with individuals with normal glucose tolerance (all p < 0.001)." (PMID 35439985, 2022). "Because these transcription factors may be involved in regulating insulin secretion as well as glucose and lipid metabolism, the HHEX gene plays important roles in carbohydrate intolerance and diabetes." (PMID 35197747, 2022). "The average insulin positive cell number in the diabetes group was much lower than the control group (p < 0.001) and the GQD or metformin treatment did not cause a significant difference in insulin cell number compared to the diabetes group (P > 0.05)." (PMID 35858880, 2022). "Diabetes is a serious, chronic disease that develops when the pancreas does not produce enough insulin or when the body does not utilize insulin effectively." (PMID 36482376, 2022). "Diabetes mellitus is a chronic metabolic disease that occurs when the pancreas is not producing enough insulin or when the insulin that it does produce is not able to be used effectively in the body." (PMID 35234250, 2022). "Among 442 youths, 112 youths had no diabetes (controls) whereas 330 youths had T1D; 182 and 148 youths with T1D had normal insulin sensitivity (T1D/IS) or insulin resistance (T1D/IR), respectively." (PMID 35303528, 2022). "The progression from early impaired fasting glucose toward overt diabetes in Alström patients is mostly due to a progressive failure in β-cell insulin secretion without any further worsening of insulin resistance." (PMID 35832432, 2022). "Type 1 diabetes mellitus (T1DM) is a progressive disease as a result of the severe destruction of islet β-cell function, and exogenous insulin is not only essential for more efficiently control of blood glucose levels, but also for T1DM patients to stay in life." (PMID 36091534, 2022).